PAX8 (paired box 8)
Diseases named in the same sentence as PAX8 in open-access papers (continued):
Sharing a sentence is not in itself a finding about the gene and the disease.
tumor (continued). "Collectively, our data highlights that tumor-specific epigenetic remodeling is tightly related to MECOM, PAX8, SOX17 and WT1 activity and these transcription factors are targetable in a tumor-specific manner through transcriptional inhibitors." (PMID 37090516, 2023). "Of the neoantigens with a strong affinity, four originated from tumor related genes (ARID2, DICER1, PAX8, and PTEN)." (PMID 37932340, 2023). "The finding that some ccRCC cell lines were insensitive to PAX8 inhibition without known inhibitory challenge on PAX8 suggested that lineage factor independence could emerge naturally during tumor evolution and that this could be associated with specific molecular features." (PMID 37554444, 2023). "In a subset of usual‐type ECA cases (13/33, 39.4%), the tumor comprised mucinous epithelium exhibiting an intermediate gastric and usual phenotype and diffuse positive CLDN18 (M) and PAX8 expression." (PMID 35861118, 2023). "Tumor cells expressed TTF1, PAX8, and p63, NUT protein expression was “equivocal,” and there was no expression of thyroglobulin." (PMID 34997561, 2022). "The PAX8 protein level was also evaluated in Clinical Proteomic Tumor Analysis Consortium (CPTAC) Confirmatory/Discovery dataset by using UALCAN online software, PAX8 protein level was elevated in UCEC compared with normal tissue." (PMID 35672291, 2022). "Immunohistochemically, the tumor cells diffusely expressed S100, alpha-inhibin, neuron-specific enolase (NSE), vimentin and PAX8." (PMID 35220972, 2022). "We also performed IHC multiplex staining for IL6, PAX8 (HGSOC tumor marker), and CD3 on HGSOC patient biopsies and observed IL6 brown staining colocalized in areas with purple tumor cells and some blue tumor-infiltrating lymphocytes." (PMID 35313341, 2022). "The mRNA level of paired box 8 (PAX8) changed significantly and was confirmed as an important factor in tumour‐inducing effect of ADSCs." (PMID 33830648, 2021). "The follicular epithelial origin of this tumor should be confirmed using immunohistochemistry including positivity for thyroglobulin (inset), thyroperoxidase, TTF1, PAX8, and cytokeratins (clone AE1/AE3)." (PMID 32632840, 2020). "By immunohistochemistry, the tumor cells are positive for high- and low-molecular-weight keratins and usually positive for thyroglobulin, TTF1, and PAX8." (PMID 32632840, 2020). "All tumors from either origin ubiquitously stained for PAX8 —a well-known marker for HG-SOC, with the exception of solid tumors that consisted of both glandular and mesenchymal-like tumor cells." (PMID 32461556, 2020). "It revealed that the VOA1066 primary tumor cells lost the expression of four epithelial markers including ER, cytokeratin-7 (CK7), EMA and PAX8, which were retained in the epithelial cells of the adjacent normal endocervix tissue." (PMID 33052929, 2020). "The PAX8/PPAR fusion results in significant increases in expression of PAX8/PPAR chimeric protein and, as a result, inhibits the tumor suppressor activity of PPAR." (PMID 32370142, 2020). "Other than clinical history, IHC positivity for CK7, ER and, paired box 8 (PAX-8) matched with negativity for CK20, support the Mullerian origin of the tumor." (PMID 32759682, 2020). "Among the upregulated genes in the tumors compared to those in the normal tissue, we found CKAP4, DUSP1, PAX8, AP1M2, C-KIT and NOTCH3, with NOTCH3 being the only gene that was upregulated in all tumor types." (PMID 31159852, 2019). "The tumor cells were positive for TTF1, PAX8 and thyroglobulin, and the proliferation indexes were 4% and 1,9% respectively." (PMID 31699114, 2019). "It is worth noting that the number of tumours exhibiting BRAF K601E, TERT, RET/PTC1, and PAX8-PPARγ were too low to establish statistical significance." (PMID 31623671, 2019). "Pathological examination of the tumor along with immunohistochemistry-showing positivity for CAIX, CD10, Vimentin, and PAX-8-pointed to a diagnosis of metastatic clear cell RCC." (PMID 31440470, 2019).
tumor (continued). "Immunohistochemical analyses confirmed the tumor as thyroid-derived, as the cells were uniformly positive for cytokeratin MNF116, PAX8 and TTF1." (PMID 31699114, 2019). "Immunohistochemically, the tumor cells were diffuse moderately or strongly positive for CD10, P504S, vimentin, PAX8, RCC, AE1/AE3, and SDHB and focally positive for CK7 and CA IX while negative for cathepsin K, HMB45, Melan-A, Ksp-cadherin, and CD117." (PMID 31828108, 2019). "Conceivably, these PAX8 regulon elements are involved in decisive events that determine cell fate and phenotype during Müllerian duct organogenesis, and in the context of oncogenesis, may undergo dysregulation to assist ovarian malignant transformation and tumor progression." (PMID 31050342, 2019). "Immunohistochemically, the tumor cells were diffuse and strongly positive (+++) or moderately positive (++) for CD10, P504S, vimentin, PAX8, RCC, AE1/AE3, and SDHB." (PMID 31828108, 2019). "Pathology of tumors showed characteristic ELST morphology with immunoexpression of CK7, GFAP, S100, PAX-8, PAX-2, CA-9 in the tumor cells." (PMID 30340515, 2018). "Known epithelial HGSOC markers such as MSLN, PAX8 and KRT7 were higher in the FTEC isolates, HGSOC tumours and group I cell lines compared with groups II and III cell lines (including IOSEs)." (PMID 27561551, 2016). "Previous research has shown that PAX8 knockdown in HGSC leads to apoptosis as well as an increase in migration, anchorage independent growth, and tumor suppression." (PMID 27129161, 2016). "If our interpretation of the Nes-Cre- and Pax8+/Cre-driven Wt1 mutants and how they compare to WT1-mutant and WT1-wild-type tumours is correct, our data also highlights other differences between these two tumour groups." (PMID 26035382, 2015). "The immunohistochemical profile of the current tumor is comparable to previously reported TLFCK cases (AE1/AE3+, CK7+, PAX-2+, PAX-8+, vimentin+, EMA+, TTF-1−, TG−, CD56−, WT-1−, CD10−, and CEA−)." (PMID 25133003, 2014). "Furthermore, re-expression of PAX8 could promote iodine accumulation in human tumor cells." (PMID 23917811, 2013). "Of these, eight showed highly significant hypermethylation in tumor tissue (p < 0.0001): GDNF, MTHFR, OPCML, TNFRSF25, TCF21, PAX8, PTPRN2 and PITX2." (PMID 18616821, 2008). "Immunohistochemical analysis of the tumor specimen demonstrated that the tumor was PAX8 positive and GATA3 negative, consistent with the pathological findings of the current case." (PMID 40979509, 2025). "Tumor cells were positive for PAX8 and AMACR, while negative for CK7, 34BE12 and SF-1, and have retained SMARCB1 (INI-1), FH, SDHB and BRG-1 expression." (PMID 39996894, 2025). "PAX8 positivity confirmed the renal origin of the tumor, as this marker is not typically expressed in primary GI malignancies." (PMID 40600205, 2025). "Tumor cells were weakly positive for synaptophysin and PAX8 but negative for markers commonly used to distinguish thymic, germ cell, and metastatic carcinomas." (PMID 40421964, 2025). "JFE-21 cells were CK7 positive, CK20 negative and PAX8 positive, a pattern identical to the patient’s tumor tissue and consistent with carcinomas arising from the ovary." (PMID 39878900, 2025). "The absence of PAX8 expression, commonly used to mark the Müllerian epithelium, supports the extra-Müllerian differentiation of this tumor." (PMID 40700236, 2025).
tumor (continued). "In conclusion, patient-derived organoids were successfully established from PARPi-resistant HGSOC cell lines, retaining the original tumor architecture and biomarker expression (EpCAM, CA125, PAX8, HER2, MEK1/2, Cyclin E1), thus validating their use as preclinical models." (PMID 41009433, 2025). "Immunohistochemical stains showed the tumor cells were overwhelmingly negative for PAX8; however, the scant clusters of epithelioid cells appeared strongly PAX8 positive." (PMID 39833894, 2025). "Immunohistochemical (IHC) staining was non-specific for tumor origin, showing positivity for calretinin, weak positivity for synaptophysin and PAX8, and scattered staining for AE1/3, Cam5.2, and EMA." (PMID 40421964, 2025). "Immunohistochemical analysis showed that the tumor cells were positive for PAX8, CA-9, CD10, and CK7, but negative for CD117 and TFE3." (PMID 41426332, 2025). "Histopathological and immunohistochemical analyses confirmed that these organoids recapitulated the architectural and molecular features of the original tumors, including expression of established tumor markers (EpCAM, CA125, PAX8) and potential therapeutic targets (HER2, MEK1/2, Cyclin E1)." (PMID 41009433, 2025). "The tumor closely resembled FATPWO both morphologically and immunophenotypically, exhibiting loss of PAX8 and cytokeratin 7 expression, with no identifiable recurrent molecular alterations." (PMID 40959354, 2025). "In addition, both the patient’s tumour tissue and MTC-22 cells were doubly-positive for CK7 and PAX8." (PMID 38573494, 2024). "Through immunofluorescence experiments, we observed that LAG3 expression is observed in immune cells (CD45+ cells) rather than in tumor cells (PAX8+ cells)." (PMID 38277212, 2024). "This is all the more true since other important tumor entities that often metastasize were almost always PAX8 negative." (PMID 39105782, 2024). "By IHC, the tumor cells were diffusely positive for GATA3 and PAX8." (PMID 39469368, 2024). "For most of these PAX8-negative tumor types, several other studies have described significant PAX8 positivity rates often exceeding 20% or even 50%." (PMID 39105782, 2024). "Herein, the expression of PAX8 did not enable the tumor classification, likely due to the small size of our series, suggesting that the most important immunohistochemical feature is the comparison of the CK7/CK20 expression." (PMID 38341381, 2024). "Immunostains performed on the tumor cells within the cell block were positive for cytokeratin 7 (CK7), TTF-1, napsin-A, and weak patchy for paired-box gene 8 (PAX8)." (PMID 39318937, 2024). "Quantitative analysis demonstrated that NIS, PAX8, NKX2.1, TG, TPO and Hhex levels were significantly decreased upon METTL3 deletion, which suggests that METTL3 promotes TC dedifferentiation and performs a tumour suppressor role." (PMID 38993572, 2024). "That PAX8 positivity was also seen in 88 cancers from 118 tumor entities that were not derived from thyroid, kidney, or the female genital tract represents a diagnostic challenge." (PMID 39105782, 2024). "These tumours retain to a certain extent the expression of epithelial-origin antibodies (pancytokeratin and/or EMA) and renal-cell-origin antibodies (PAX8, CD10, CAIX) though they may be focal and weak." (PMID 39744248, 2024). "For the distinction between a renal cell origin and a non-renal origin of tumors (including all other tumor entities of our study), sensitivity was 88.1% and specificity 87.2% for PAX8, while sensitivity was 85.3% and specificity 95.7% for CDH16." (PMID 39105782, 2024).
tumor (continued). "Based on our comparison of MSVA-708R and MRQ-50, we assume that very high positivity rates in many tumor entities that were largely PAX8 negative in our cohort were driven by similar antibody-specific cross-reactivities." (PMID 39105782, 2024). "However, the tumor’s histology completely matched that of ovarian CCA, and the tumor cells expressed specific markers CK7, PAX-8, NapsinA, and HNF-1β, consistent with the immunophenotype of female genital tract ovarian CCA." (PMID 39533590, 2024). "Once again, our results suggested that spheroids were composed of only tumor cells, as nearly all cells in spheroids were positive for PAX8 and negative for vimentin." (PMID 36875739, 2023). "Notably, more EVs were PAX8 and HGSOC‐marker positive in tumor samples, validating the presence of FT‐derived tumor EVs in circulation." (PMID 37485618, 2023). "Immunohistochemically, tumours expressed CK7, AMACR and PAX8." (PMID 37649003, 2023). "The tumour cells were also positive for GATA3, E-cadherin, Pax-8, Succinate dehydrogenase B (SDHB) and Fumarate hydratase (FH), and negative for vimentin, Carbonic anhydrase 9 (CA9), CD10, P504s, CK20, TFE3, TFEB, HMB45, ALK and Forkhead box protein I1 (FOXI1)." (PMID 36816543, 2023). "As the tumour cells consistently expressed cytokeratin 7 and PAX8 in absence of cytokeratin 20, carcinoembryonic antigen (CEA) and pancytokeratine, we diagnosed endometrial carcinoma metastatic to the skin in all three locations." (PMID 37013123, 2023). "The tumor showed positive staining for CD56, PAX-8, and CAM5.2." (PMID 37072571, 2023). "No significant changes were observed in tetraspanin‐positive EV numbers between no‐tumor (Day 0) and tumor (Day 30) samples, whereas PAX8‐positive EV numbers significantly increased in the tumor samples." (PMID 37485618, 2023). "This tumor is never immunohistochemically positive for markers expressed by all other tumors derived from the follicular epithelial cell like thyroglobulin or PAX8." (PMID 37249797, 2023). "For the other three genes (MUC16, PAX8 and SOX17) in combination, their RNA quantity may distinguish OSCA from other 29 tumor types." (PMID 35954427, 2022). "As per immunohistochemistry, the tumor cells were diffusely positive for SF-1 and Ki-67, partially positive for inhibin, and negative for CAM5.2, CK7, CK20, C-KIT, CD30, LCA, GATA-3, TTF-1, and PAX8." (PMID 36335378, 2022). "Besides CA9, the tumor cells additionally expressed CD10, another marker of ccRCC, and PAX8, proving their renal epithelial origin." (PMID 35646693, 2022). "In this study, for all cases tested, the tumor cells are positive for PAX8, GATA3, TTF1, and luminal CD10, and are negative for ER and PR, consistent with the immunohistochemical results previously reported." (PMID 35865471, 2022). "The lower part of the collecting system arises from the PAX8-negative urogenital sinus, and tumors that arise from the lower part, i.e., tumors of the ureters and bladder, are all PAX8-negative." (PMID 35806410, 2022). "Positive staining of CK20, CDX-2, STAB2, and negative staining of CK7 and PAX-8 was observed for the tumor tissue, indicating that the tumor was of gastrointestinal adenocarcinoma origin, rather than ovarian origin." (PMID 35721089, 2022). "Immunohistochemistry showed that the tumor cells were diffusely positive for SF-1 and Ki-67, partially positive for inhibin, and negative for CAM5.2, CK7, CK20, C-KIT, CD30, LCA, GATA-3, TTF-1, and PAX8." (PMID 36335378, 2022). "We found that the knock down of FAM83B significantly affect normal and tumor thyroid cell differentiation, inducing in NTHY-ORI a reduction in the expression of the thyroid marker genes PAX8 and NIS, and in TPC1 cells a significant increase in the expression of the mesenchimal marker vimentin." (PMID 35597845, 2022).
tumor (continued). "FTE markers (PAX8, KRT7) were highly expressed in all subclusters of epithelial cells, indicating that the tumor may originate from fallopian tube." (PMID 36248860, 2022). "The fact that the genes positively regulated by PAX8 and MECOM also stratify patients with poorer prognosis suggests that indeed PAX8 cooperates with MECOM to regulate a gene expression program that promotes aggressive tumor phenotypes." (PMID 33903593, 2021). "For the TSHR-KO mice we used highly purified ES cells selected for Pax8 and NKx-2.1 expression and we have seen no tumor formation to date." (PMID 34276566, 2021). "However, no research is currently available on the relationship between tumor size and PAX2 and PAX8 expression." (PMID 34306127, 2021). "PAX8 can potentially regulate cancer progression, that is ADSC‐induced tumour development, and participated in modulating the interaction between TME and primary tumours." (PMID 33830648, 2021). "The tumor cells in all 7 cases expressed IHC stains for PAX8, ER and CK7 and PR and were negative for CK20, CDX2 and WT1." (PMID 33736662, 2021). "Having previously established that PAX8 is necessary for RB protein stability (PAX8 can regulate E2F1 transcription and stabilize RB protein to promote tumour cell proliferation), we hypothesized that PAX8 could also regulate TAZ in protein level." (PMID 33830648, 2021). "We evaluated demographic data and tumor characteristics regarding PAX2 and PAX8 expression." (PMID 34306127, 2021). "Comparison between unpaired and paired tumor and adjacent normal tissues from the KIRC cohort revealed that the expression of PAX8 and HNF1B was downregulated in tumor tissues, which might be different from some ccRCC cell lines." (PMID 33850477, 2021). "Upon immunohistochemistry, the tumor cells stained positive for vimentin and Pax-8, whereas they were negative for CK7 and Ca19-9, and were therefore diagnosed as ccRCC metastases." (PMID 34059139, 2021). "Additional immunohistochemistry was performed, the tumor cells were positive for PAX8 and partly for CK7 and negative for SATB2 and CK20, confirming their gynecological and not colorectal origin." (PMID 33670088, 2021). "While we do also observe in our PAX8 ChIP-seq dataset a strong enrichment for TEAD motifs, our study focuses on MECOM interaction as we readily identified it in BioID experiments and demonstrate that MECOM is necessary for in vivo tumor growth." (PMID 33903593, 2021). "The healthy control slides were negative for the tumour markers (CK/EpCAM, PAX8 and vimentin), but a few WBCs showed co-expression of PD-L1 and CD16/45." (PMID 34944844, 2021). "All mice with the same transgene, but without doxycycline administration, were free of tumor at all time points examined, indicating that there was minimal leakage of the Pax8-Cre induction system." (PMID 32483112, 2020). "By contrast, OCM.87 was positive for PAX8, EpCAM and CA125 and thus confirmed as a tumour model." (PMID 32054838, 2020). "The immunohistochemical profile showed tumor cells that express Melan-A and smooth muscle actin, while they were negative for pan-cytokeratin, PAX8, CK7, CD117 and CD34." (PMID 33344317, 2020). "The tumor cells express cytokeratin 7 (CK7), cytokeratin 5-6 (CK5-6), cancer antigen 125 (CA125), estrogen (ER), progesterone (PR), Wilm's tumor gene (WT1), paired box gene 8 (PAX8), Ber-EP4, and epithelial membrane antigen (EMA)." (PMID 33062370, 2020). "Immunohistochemical (IHC) staining was performed using thyroid transcription factor-1 (TTF-1), paired box protein 8 (PAX8), cytokeratin 20 (CK20), caudal-related homeobox transcription factor-2 (CDX-2) and villi protein (Villin) in order to clarify the origin of the tumor." (PMID 32375670, 2020).